SNAI1 (snail family transcriptional repressor 1)
Diseases named in the same sentence as SNAI1 in open-access papers (continued):
Sharing a sentence is not in itself a finding about the gene and the disease.
tumor (continued). "Once this process is under way in a tumor, it is typical to find a coordinated alteration in the expression of all these genes: the expression of ZEB1, ZEB2, VIM, and SNAI1 is upregulated, while the expression of CDH1 is downregulated." (PMID 25157365, 2014). "Screenings as done herein exemplarily for the HMGA2 regulator let-7a and the HMGA2 targets HMGA1, SNAI1, SNAI2 and CDH1 will help to reveal the tumour acting mechanisms." (PMID 24914948, 2014). "Next, we explored the potential mechanism by which SNAI1 enhances reprogramming, noting the references that link EMT with downregulation of the let-7 family of tumor suppressor miRs." (PMID 25316190, 2014). "Overexpression of HIF-1α and SNAI1 in HCC samples were shown to be correlated with pathological classification, TNM staging and tumor volume (P < 0.05)." (PMID 23496980, 2013). "In other tumor models, EGF was shown to trigger an EMT with up-regulation of either SNAI1 or TWIST1 possibly through STAT3 activation." (PMID 22272264, 2012). "The constitutive expression of SNAI1 and CDH1 in RB tumor tissues revealed the inverse correlation between them." (PMID 23077401, 2012). "Snai1 was inversely associated with a positive estrogen receptor status (p = 0.041), but not with the progesterone receptor (p = 0.58) nor with the size of the tumor (p = 0.301), presence of metastases (p = 0.57), grade of tumor (P = 0.10, grade I-II/III) or HER2 amplification (p = 0.215)." (PMID 21324165, 2011). "SNAI1 expression in our series of OSCC was found to occur as an infrequent event that was mostly observed in few, scattered tumor cells representing less than 5% of the entire tumor population." (PMID 20181105, 2010). "The connection including TGM2, IL1B, and PLAU and the connection including RAB25, SNAI1, and CDH1 were suggested to be related to tumor invasion by IPA." (PMID 20142997, 2010). "In cancer, such transcription factors, like Snail/SNAI1, Slug/SNAI2 and ZEB1, often become deregulated and promote tumor progression." (PMID 20860828, 2010). "The second connection including RAB25, SNAI1, and CDH1 was suggested to be related to tumor invasion." (PMID 20142997, 2010). "Interestingly, only PPARD expression positively correlated with an EMT-related gene signature formed by ZEB1, SNAI1, and SNAI2 in the tumor." (PMID 40607925, 2025). "Furthermore, we identify Snai1 as a deubiquitination target of USP47, explaining USP47-dependent activation of the epithelial-mesenchymal transition pathway and tumor progression." (PMID 39998882, 2025). "In BC cells, the signaling pathways TNFα/NFκB and IL6/STAT3 are known to promote tumor progression via activation of key EMT-related transcription factors, such as Snail Family Transcriptional Repressor 1 (Snail1), Twist-related protein 1 (Twist1), and Zinc finger E-box binding homeobox 1 (ZEB1)." (PMID 40807456, 2025). "SNAI1 and SNAI2 are key regulators of tumor metastasis and drug resistance." (PMID 39708716, 2025). "Dovitinib, an inhibitor of multiple receptor tyrosine kinases, is reported to induce the activation of tumor‐intrinsic SNAI1/2‐IFN‐γ signaling and suppress EMT in another recent study, which promotes T cell recruitment and makes mesenchymal‐like tumor to be sensitive to CTLA4 blockade." (PMID 39092293, 2024). "Furthermore, we examined the expression of several most well-known EMT-related genes (N-cadherin, SNAI1, Vimentin) and observed that ALDH18A1 knockdown suppressed the EMT process, indicating a reduced capacity for tumor migration." (PMID 38970690, 2024). "We examined their unique cell morphology characteristics (A) and analyzed a wide range of tumor markers (B), including the PD‐1/PD‐L1 status, PD‐L2 expression, EMT markers (vimentin, E‐cadherin, and N‐cadherin), oncogenes (TWIST and Snai1), and the HNC stem cell marker CD44." (PMID 38103190, 2024).
tumor (continued). "SNAI1 also known as ZEB2 (zinc finger E-box binding homeobox 2), as well as ZEB1, E2-2 (as also known as transcription factor 4) and Twist, were all up-regulated in ECSs, similar to other tumor types." (PMID 38836981, 2024). "Because of these manifold effects on both the tumor cells and the TME, we used overexpression of Snai1 and Twist1 to test the potential of our platform to evaluate the effect of the misregulation of individual genes in different cellular components of the tumor." (PMID 38678014, 2024). "Meanwhile, the increase in MMP-2 MMP-9, SNAI1 and TWIST1 protein levels in the IL-22 group suggests that IL-22 may regulate MMP expression by activating the PI3K/AKT signaling pathway, enhancing tumor cell invasion and metastasis." (PMID 39073546, 2024). "Moreover, the expressions of TIMP1, PGF, FSTL3, SNAI1, and FOXC1 were significantly up‐regulated in the tumor tissues." (PMID 37017587, 2023). "Low expression of SNAI1, CDR2L, FRMD5, and FSTL3 could induce cell viability and promote tumor cell apoptosis." (PMID 36925652, 2023). "Similar to Snai1 knockout fibroblasts, EDA- fibronectin fibroblasts produce an extracellular matrix that does not sustain TGFβ-induced fiber organization, rigidity, fibroblast activation, or tumor cell invasion." (PMID 37964360, 2023). "β-catenin promotes tumour development by regulating the expression of immune escape-related molecules (CCL4, CD47 and PD-L1) through transcription factors (MYC, TCF/LEF, NF-κβ, SNAI1, etc.)." (PMID 36646807, 2023). "AXL tyrosine kinase promotes tumor progression through serine/threonine protein kinase (AKT)/GSK-3β/β-catenin signaling, β-catenin nuclear-translocation-induced snail family transcriptional repressor 1 (SNAIL) transcription, and activation of MMP-2 and MMP-9." (PMID 37046676, 2023). "Snai1 KO and EDA– fibronectin MEFs behave similarly: They deposit matrices that do not sustain rigidity, fiber organization, metalloproteinase resistance, fibroblast activation or tumor cell invasion." (PMID 37964360, 2023). "We did not detect SNAI1 on myeloid cells in our tumours or in additional immune populations as assessed by CD45 staining." (PMID 37516803, 2023). "The results demonstrated that RGS16, SNAI1, CDR2L, FRMD5, and FSTL3 consistently exhibited significantly higher relative mRNA expression levels in CC tumor samples than in paired adjacent normal tissues." (PMID 36925652, 2023). "The researchers found that circ-0001666 acts as a sponge of miR-1251, the circRNA-associated ceRNA network further up-regulates SOX4, and circRTN4 regulates the expression of Slug, Snai1, Twist, Zeb1, and N-cadherin in the EMT pathway by interacting with tumor suppressor miR-497-5p." (PMID 35806027, 2022). "These chemotactic factors recruit neutrophils to tumor sites and generate reactive oxygen species through phosphatidylinositol 3-kinase (PI3K)/protein kinase B (AKT)/zinc finger protein SNAI1 (Snail) signaling, inhibiting EMT and converting neutrophils to an antitumor phenotype." (PMID 36060811, 2022). "We have previously reported that the EMT-TFs SNAI1 and ZEB1 are involved in the direct overexpression of the programmed cell death protein ligand-1 (PD-L1) and the macrophage immune checkpoint CD47 on tumor cells." (PMID 36465484, 2022). "The anti-tumour effects of Rec8 are caused by downregulation of cell growth-related genes (G6PD, SLC2A1, NOL3, MCM2, SNAI1, and SNAI2) and also by upregulation of both apoptosis or migration inhibitors (Gadd45G and LDHA) and tumour inhibitors (PinX1, IGFBP3, and ETS2)." (PMID 36139540, 2022). "In their study, Liu D. and colleagues showed that HCV core protein was able to induce EMT in normal hepatocytes and HCC tumor cells through the down-regulation of E-cadherin and the up-regulation of EMT markers, such as vimentin, Snail Family Transcriptional Repressor 1 (SNAL1), and SNAL2." (PMID 34069740, 2021).
tumor (continued). "For instance, the epithelial to mesenchymal transition (EMT)-regulators zinc finger E-box- binding homeobox-(ZEB)-1 and -2, snail family transcriptional repressor 2 (SLUG), snail family transcriptional repressor 1 (SNAI1) and TWIST-related protein 1 (TWIST) are critical drivers of tumor progression." (PMID 34439247, 2021). "SNAI1 is a master regulator of cancer EMT, whose overexpression correlates to tumor aggressiveness." (PMID 34455105, 2021). "Current research suggests that EMT transcription factors like SNAI1, TWIST1 and ZEB1 may contribute to the promotion of tumor metastasis and drug resistance by EMT." (PMID 35127731, 2021). "Interestingly, HDAC2 can also be recruited by the HOP homeobox to epigenetically inhibit SNAI1 transcription, leading to the enhanced histone H3K9 deacetylation, which subsequently suppresses tumor progression." (PMID 34681726, 2021). "In addition, TWIST induces SNAI1 and the Twist-SNAI1 axis is critically involved in EMT and tumor metastasis." (PMID 34681726, 2021). "Notably, we show here that upon ALKBH5 overexpression, the stabilized FBXL5 further elicited the downregulation of the IRP2 and SNAI1 proteins, both of which are substrates ubiquitinated by FBXL5 and are crucial drivers of tumor progression." (PMID 34733841, 2021). "Therefore, FBXL5-induced degradation of SNAI1 protein and subsequent EMT changes also contributed to hinder tumor progression of PDAC." (PMID 34733841, 2021). "A previous study has shown ID1 to inhibit TWIST-mediated EMT to promote mesenchymal–epithelial transition at metastatic sites where SNAI1 expression is low and underscores that ID1 does not affect SNAI1-mediated EMT at the primary tumor site." (PMID 34869246, 2021). "Specifically, SNAI1 expression was negative closely related with infiltrating levels of tumor purity and B cell in STAD, and positively closely related with macrophages in STAD." (PMID 32833672, 2020). "As in the previous tumor lines, SLUG and SNAI1 are downregulated by the treatment with FH535." (PMID 32784485, 2020). "SNAI1 is an important EMT transcription factor that regulates EMT progression by inhibiting the migration of E-cadherin and enhancing the migration and invasion of tumor cells." (PMID 32226772, 2020). "The expressions of FIR family and Snai1 were significantly higher in tumor tissues (T) than in their non-cancerous counterparts (N)." (PMID 32071290, 2020). "However, a large number of genes considered as oncogenes or that promote tumour growth and/or metastasis, such as SKI, EGR4, SNAI1 and CEMIP2, were also overexpressed in response to TPL." (PMID 32543350, 2020). "Alternatively, ITGB4 could bind to PD-L1 to promote SNAI1 and AKT/GSK3β signaling, which in turn activates glycolysis and tumor metastasis." (PMID 32839493, 2020). "This study and others showed that snail family zinc finger 1 (SNAI1) could act as a direct target of miR-153 and promote cell invasiveness and tumor progression." (PMID 31200531, 2019). "Furthermore, CAR10 knockout successfully decreased the expression of SNAI1 and SNAI2 and inhibited tumor proliferation and metastasis in vivo." (PMID 30617305, 2019). "Therefore, a strategic method to segregate patients harbouring SNAI1 and HDAC dependency during tumour progression is essential to efficiently use existing HDAC inhibitors as cancer therapeutics." (PMID 31165775, 2019). "However, other studies indicate that XBP1s increases the metastatic potential of tumor cells by the induction of the expression of several EMT transcription factors, including SNAI1, SNAI2, ZEB2 and TCF3." (PMID 31064137, 2019). "For both cell line and tumor pieces, evaluation of gene expression demonstrates high endogenous expression of select mesenchymal genes (VIM, cMYC, FRA1, SNAI1 and SLUG), and low endogenous expressions of epithelial gene CD24 and mesenchymal genes TWIST and ZEB1." (PMID 30845999, 2019).
tumor (continued). "This seemingly paradoxical finding can be potentially explained by a recent study suggesting that SNAI1 is not absolutely needed for the physical migration of cells, but contributes to increased tumor survival and drug resistance." (PMID 30034631, 2018). "We studied a retrospective cohort of 160 consecutive surgically treated NSCLC patients with available frozen tumor samples for expression of EMT markers (CDH1, CTNNB1, CDH2, and VIMENTIN), inducers (TGFB1, c‐MET, and CAIX), and transcription factors (EMT‐TF:SNAI1, SNAI2, ZEB1, TWIST1, and TWIST2)." (PMID 29845746, 2018). "In some tumor types, it blocked EMT and tumor progression, while in others induced EMT-TFs expression and EMT, like we observed in the induction of SNAI1, SNAI2 and ZEB1 expression in MCF7 cells after 5-aza treatment alone or in combination with the SIRT1 inhibitor." (PMID 30445998, 2018). "SNAI1 was also shown to induce the expression of mesenchymal markers fibronectin and Zeb1, the latter of which is an EMT‐TF that can promote tumor invasiveness in vitro and is correlated with tumor cell differentiation in vivo." (PMID 28548345, 2017). "Members of the EMT regulating transcription factor families such as SNAI1/2, TWIST1/2 and ZEB1/2, are well-known as key inducers of invasion and metastasis in epithelial cancers through the conversion of tumour cells from an epithelial to a mesenchymal-like state." (PMID 27470974, 2016). "From another perspective, regarding whether SNAI1 is a target for the biological treatment of HCC, we observed the role of lentiviral‐mediated RNAi vectors against SNAI1 using a nude mouse tumor model in vivo." (PMID 27239445, 2016). "Expression level of FCGR1A, although not correlated with VIM or CDH1, had r = 0.31 and r = 0.42 with SNAI1 and SNAI3 respectively, suggesting it may be co-expressed with these EMT drivers in some tumours." (PMID 27876705, 2016). "In addition, the regulator Snail (SNAI1), which mediates EMT activation for metastatic dissemination of cancer cells from the primary tumor, is targeted by miR-30a." (PMID 26918943, 2016). "SNAI1 and SNAI3 induction did not associate with a specific tumor subtype and were not correlated one to each other." (PMID 24638100, 2014). "SNAI1 comes from the zinc-finger superfamily of SNAIL, which is dysregulated in numerous neoplasms." (PMID 24959930, 2014). "Interestingly, the levels of SRC and PPARB/D expression were highly and significantly correlated in these tumours, as were the expression levels of PPARB/D andTGFB1 and MMP19, respectively, and to a lesser extent, MMP2, VEGFA, VIM and SNAI1." (PMID 24203162, 2014). "We have not observed any statistically significant correlation between expression of VIM, TWIST1 or SNAI1 (analyzed together or separately) in CTCs-EBF and histological type of the tumor (ductal vs. lobular, p = 0.48) or molecular subtype of the primary tumor (p = 0.93, data not shown)." (PMID 24217115, 2013). "These genes were significantly upregulated in the group 2 DIPGs relative to the group 1 tumours (GSEA analysis: enrichment score 0.56, FDRq = 0.039, p nominal = 0.034), together with the master epithelial-mesenchymal transition regulators, SNAI1 and SNAI2/Slug genes." (PMID 22389665, 2012). "SNAI1 is an effector transcription factor that has been shown to induce the EMT through direct suppression of E-cadherin transcription in cancer and thus contribute to tumor cell growth, migration and invasion." (PMID 23185371, 2012). "Previous studies have focused mainly on nuclear and cytoplasmic expression of TWIST and SNAI1 in epithelial cancer cells, not on the whole tumor microenvironment." (PMID 21834956, 2011). "Two recent studies which examined SNAI1 in HNSCC by IHC were not able to detect substantial expression of the protein in the epithelial tumor component." (PMID 20181105, 2010). "The lymph node metastasis in this case was strikingly p63 negative, but displayed SNAI1 expression in only 10% of all tumor cells." (PMID 20181105, 2010).
tumor (continued). "Furthermore, high HSPB1 expression may have triggered EMT-related genes (SNAI1, SNAI2, SOX10), suggesting a complex dual effect of 2S-13 on tumor plasticity." (PMID 41007338, 2025). "Indeed, some of these TFs such as SNAI1 and ZEB1 were shown to induce EMT in most of the tumor cell/tissue types tested, while few others such as GATA4, GATA6, PRRX1 etc. were found to promote EMT in certain cell/tissue types only, and even block the EMT process in others." (PMID 34708244, 2022). "In a mouse tumor model, it was shown that radiation therapy triggers the secretion of CXCL1, CXCL2, and CCL5, which leads to neutrophil recruitment to tumor sites; in turn, neutrophils generate ROS and suppress PI3K/AKT/SNAI1 signaling, inhibiting epithelial–mesenchymal transition." (PMID 36555469, 2022). "Another hypothesis is that EMT-TFs expression is organ (and therefore) tumor specific, e.g., Snai1 and Twist1 are not necessary in mouse model of pancreatic cancer, while Zeb1 knock-out reduces metastasis of about 30%." (PMID 34768901, 2021). "Additionally, overexpression of different EMT-TFs, including Slug, Twist, Six1 and Snai1, promoted stemness and tumor initiation capacity, whilst EMT-TF knockout had a tumor-preventative effect (e.g., Slug-knockout mice were resistant to MMTV-Myc-induced tumor initiation)." (PMID 34072345, 2021). "The MTT test, propidium iodide/AnnexinV in-vitro, and tumor volume measurement using the QRT-PCR test with the 2−ΔΔCT method were used to estimate the inhibition of miR-21 and the expression of downstream genes including: SNAI1, Nestin (Nes), Oct-4, and NF-kB following miR-21 inhibition." (PMID 32788885, 2020). "Moreover, SNAI1 expression was negative closely related with infiltrating levels of tumor purity and B cell in COAD, and positively closely related with CD4+T cells, macrophages, dendritic cells, and neutrophils in COAD." (PMID 32833672, 2020). "SNAI1 levels measured in patients PBMCs indicated that this transcription factor is significantly increased in patients who had no residual tumor (n = 11, ypT0) (p = 0.025) or diseased lymph nodes (n = 13, ypN0) after NAC and in pathological complete responders (n = 8, pCR) (p = 0.018)." (PMID 31106153, 2019). "Notably, in tumor tissues of the CRISPR-CAR10 nude mice model, the knockout of CAR10 also increased miR-30 and miR-203 expression levels and decreased the mRNA and protein expression levels of SNAI1 and SNAI2." (PMID 30617305, 2019). "Three of the up-regulated cancer stem cell-related genes (KLF4, MYC, and SNAI1) are transcription factors involved in rearrangement of the extracellular matrix and in epithelial to mesenchymal transition (EMT), processes that are important in tumor angiogenesis, invasion, and metastasis." (PMID 29765518, 2018). "Meanwhile, the distinct expression pattern of SNAI1 and SNAI2 in cancer cells and fibroblasts coincides with the context-dependent role of TFs, for which the expression shift implied a unique role for SNAI1 and SNAI2 in the tumor and stromal compartment, respectively." (PMID 29041931, 2017). "Finally, in the group of cases with "rare/occasional" SNAI1 expression in tumor stroma, 2/15 corresponding tumors were negative, 6/15 had SNAI1 expression in <5% tumors cells and 7/15 were categorized as SNAI1-positive (≥ 5%)." (PMID 20181105, 2010). "The expression of MYC, NR5A2, and SNAI1 was found to be higher in EC-adjacent tissues than in samples from cancer-free patients, which shows that tumor-surrounding tissues presented truly elevated expression, not just higher expression than in a tumor because of a decreased tumor expression." (PMID 36140779, 2022). "Elevated expression of the CD133 and SNAI1 proteins in “acidified” EVs was confirmed by Western blotting that together with the data on the miR-7 and miR-221 miRNA expression point on the stronger tumor-promoting properties of “acidified” EVs in comparison to normal ones." (PMID 35327461, 2022).